TAF1C (TATA-box binding protein associated factor, RNA polymerase I subunit C)
Description:
Component of the transcription factor SL1/TIF-IB complex, which is involved in the assembly of the PIC (pre-initiation complex) during RNA polymerase I-dependent transcription. The rate of PIC formation probably is primarily dependent on the rate of association of SL1/TIF-IB with the rDNA promoter. SL1/TIF-IB is involved in stabilization of nucleolar transcription factor 1/UBTF on rDNA. Formation of SL1/TIF-IB excludes the association of TBP with TFIID subunits. Recruits RNA polymerase I to the rRNA gene promoter via interaction with RRN3.
Synonyms: TAFI110; TAFI95; SL1; MGC:39976
Tractability: PROTAC: ubiquitination databases record sites on it.
Gene: Protein-coding gene on chromosome 16 (84,177,846 to 84,187,070, reverse strand). Ensembl gene ENSG00000103168.
Subcellular location: Nucleus, nucleolus
Subcellular location (Human Protein Atlas): Nucleoli fibrillar center; Nucleoplasm
Pathways (Reactome):
Gene expression (Transcription): B-WICH complex positively regulates rRNA expression; NoRC negatively regulates rRNA expression; RNA Polymerase I Promoter Escape; RNA Polymerase I Transcription Initiation; RNA Polymerase I Transcription Termination; SIRT1 negatively regulates rRNA expression
Gene Ontology:
Molecular function: protein binding; RNA polymerase I core promoter sequence-specific DNA binding; RNA polymerase I general transcription initiation factor activity
Biological process: regulation of DNA-templated transcription; transcription by RNA polymerase I; transcription by RNA polymerase II; transcription initiation at RNA polymerase I promoter; RNA polymerase I preinitiation complex assembly
Cellular component: fibrillar center; nucleolus; nucleoplasm; RNA polymerase transcription factor SL1 complex; RNA polymerase I core factor complex
Genetic constraint (gnomAD): Loss-of-function variants: 80 observed, 71.32 expected, observed/expected ratio (o/e) 1.12, 90% interval 0.94 to 1.35. The synonymous counts are far from expectation, so gnomAD's model fits this gene poorly and the ratio says little. Missense variants: 1,408 observed, 1,091.6 expected, observed/expected ratio (o/e) 1.29, 90% interval 1.23 to 1.35. Synonymous variants: 613 observed, 467.24 expected, observed/expected ratio (o/e) 1.31, 90% interval 1.23 to 1.4.
Homologues: Orthologues: chimpanzee TAF1C (98% identical), macaque TAF1C (93% identical), dog TAF1C (73% identical), pig TAF1C (72% identical), guinea pig TAF1C (71% identical), mouse Taf1c (66% identical), rat Taf1c (66% identical), tropical clawed frog taf1c (33% identical), zebrafish taf1c (24% identical).